VDR (vitamin D receptor)
Diseases named in the same sentence as VDR in open-access papers (continued):
Sharing a sentence is not in itself a finding about the gene and the disease.
urolithiasis (continued). "Similar trends were also observed in association studies of VDR gene polymorphisms in patients with urolithiasis." (PMID 28361944, 2017). "Many studies investigated the associations between these polymorphisms of VDR gene and the risk of urolithiasis." (PMID 24093218, 2013). "To data, there was no reported study which was performed to assess the effect of VDR-environment interactions on urolithiasis risk in different ethnicities and regions." (PMID 24093218, 2013). "This meta-analysis suggested that ApaI and TaqI polymorphisms in VDR gene were associated with urolithiasis risk." (PMID 24093218, 2013). "Eight studies (1210 cases and 1160 controls) that identified the association between VDR BsmI polymorphism and urolithiasis risk were included in this meta-analysis." (PMID 24093218, 2013). "Several studies analyzed the associations of Vitamin D receptor (VDR) polymorphisms with urolithiasis risk in different ethnic groups." (PMID 24093218, 2013). "Expression and nuclear activation of the Vitamin D receptor (VDR) are necessary for the effects of vitamin D. Therefore, VDR was implicated in urolithiasis." (PMID 24093218, 2013). "More studies using children population are needed to determine the associations between VDR polymorphisms and urolithiasis risk." (PMID 24093218, 2013). "This present meta-analysis systematic investigated the associations between VDR polymorphisms and urolithiasis risk." (PMID 24093218, 2013). "Thirteen studies including 1744 patients and 1944 controls addressed the association between VDR TaqI polymorphism and urolithiasis." (PMID 24093218, 2013). "This meta-analysis suggested that in the Asian subgroup, there is an increased risk of urolithiasis with the ff + Ff genotype, and VDR polymorphisms could be potential biomarkers for urolithiasis susceptibility." (PMID 37007314, 2023). "Additionally, both VDR and urokinase gene polymorphism contributes to the susceptibility of recurrent urolithiasis particularly for the Asian population in the latter." (PMID 38066480, 2023). "Unfortunately, our study is unable to conclude the involvement between VDR gene polymorphism and urolithiasis recurrence in either the Asian or Caucasian population as the population obtained for our VDR gene polymorphism analysis study is largely derived from European countries." (PMID 38066480, 2023). "Additionally, variation in the VDR and urokinase genes, particularly in the Asian population, increases the risk of developing recurrent urolithiasis." (PMID 38066480, 2023). "As a result, environmental stimuli may impress the functional variants of the VDR gene as well as serum levels of vitamin D and, hence, modify the risk of urolithiasis susceptibility, along with VDR genetic polymorphisms." (PMID 32650740, 2020). "Moreover, the role of life style, age, and gender needs be considered in the stratification analyses for VDR gene SNPs and urolithiasis predisposition." (PMID 32650740, 2020). "Second, we could not analyze the role of age, gender, lifestyle, and other genetic variations, on the adjusted association of VDR gene SNPs and urolithiasis risk." (PMID 32650740, 2020). "Our research suggested that the VDR gene variant TaqI was correlated with urolithiasis susceptibility and that the t-allele might be the risk gene and T-allele the protective gene in VDR TaqI variant." (PMID 32346382, 2020). "As a consequence, clarification of VDR gene polymorphisms contribution to the urolithiasis predisposition could be advantageous in clinics with respect to better diagnosis of subjects at risk as well as treatment with maximum efficacy." (PMID 32650740, 2020). "In our population, CO2CP and levels of uric acid and serum Na as well as polymorphism of the F allele of the VDR FokI may provide important clues to evaluate the risk of urolithiasis in Uyghur children." (PMID 30742686, 2019).
urolithiasis (continued). "FokI polymorphisms can change the VDR protein sequence to produce two proteins of different lengths; the sequence was recently reported as a candidate gene locus for some diseases, such as urolithiasis, prostate cancer and osteoporosis." (PMID 30742686, 2019). "Also, the vitamin D receptor (VDR) gene has been found related to risk of urolithiasis in some populations." (PMID 30742686, 2019). "The biochemical metabolic parameters such as CO2CP, uric acid and serum Na, and the F allele of the VDR FokI may be candidate risk factors for urolithiasis risk in Uyghur children of China." (PMID 30742686, 2019). "Therefore, we performed this meta-analysis to address the precise relationship between the VDR gene variants and urolithiasis risk." (PMID 24093218, 2013). "Second, it was the first time studying the VDR-hypercalciuria interactions on urolithiasis risk." (PMID 24093218, 2013). "In 4 out of 23 studies, the role of VDR ApaI-TaqI haplotype in urolithiasis risk was analyzed." (PMID 24093218, 2013). "The meta-analysis of the VDR gene involving 5 studies with a total of 1672 allele frequency in recurrent stone formers and 1286 allele frequency in controls, also showed a significant association with recurrent urolithiasis (overall OR = 1.22, CI 95% = 1.05–1.42, p = 0.03)." (PMID 38066480, 2023). "A bulk of studies have attempted to disclose the possible association between VDR gene SNPs and urolithiasis risk; that notwithstanding, the findings still show discrepancies and a comprehensive meta-analysis seems to be required to shed insights on the unknown conundrums." (PMID 32650740, 2020). "Therefore, any alteration in the VDR may change the calcium metabolism, thus alter the urolithiasis risk." (PMID 32650740, 2020). "Another case-control study on 60 adults aged between 18-90 years showed that VDR and CLDN genes are associated with recurrent urolithiasis." (PMID 37007314, 2023). "The currently available data with respect to the association between vitamin D receptor (VDR) gene polymorphism and risk to urolithiasis are inconclusive and inconsistent." (PMID 32650740, 2020). "Taken together, studies have recommended that VDR play an essential role in the pathogenesis of urolithiasis." (PMID 32650740, 2020). "A considerable weight of evidence supporting a role for VDR in urolithiasis was derived from GHS rats." (PMID 24093218, 2013). "Individuals possessing the urokinase gene “T” allele showed a higher risk of developing urolithiasis recurrence (OR = 2.49) with no significant heterogeneity (I2 = 0%) than VDR gene polymorphism." (PMID 38066480, 2023). "Our result showed that VDR gene polymorphism increases the risk of recurrent urolithiasis by 1.22 times with no significant heterogeneity (I2 = 36%)." (PMID 38066480, 2023). "Although our analysis did not endorse the association of VDR gene BsmI, ApaI, FokI, and TaqI SNPs with susceptibility to urolithiasis, the gene can be of beneficial applications in populations with significant associations." (PMID 32650740, 2020). "However, because the signal transducers that function downstream of calcitriol/VDR also participate in high calcemia and urinary stones, investigations into the clinical applications of VD3 and/or calcitriol should be conducted cautiously." (PMID 27473111, 2016). "But another study showed that none of the VDR ApaI, BsmI, and TaqI polymorphisms created any significant risk for urolithiasis." (PMID 27688524, 2016). "VDR was one of the most studied candidate genes for urolithiasis." (PMID 24093218, 2013). "After reading the titles and abstracts, 127 articles were removed owing to abstracts, reviews, non-clinical studies, not case–control studies, and irrelevant to urolithiasis or VDR polymorphisms." (PMID 24093218, 2013). "We did not evaluate the associations between VDR polymorphisms and urolithiasis risk in children due to insufficient data." (PMID 24093218, 2013).
urolithiasis (continued). "Taken together, these results suggested that VDR may play an important role in the pathogenesis of urolithiasis." (PMID 24093218, 2013). "Finally, we only managed to perform an analysis of VDR and urokinase gene polymorphism on recurrent urolithiasis due to a lack of studies regarding other genetic polymorphism and recurrent urolithiasis." (PMID 38066480, 2023). "However, we noticed that VDR, a gene closely related to urolithiasis, was present in the network." (PMID 37569334, 2023). "Because of lacking studies of urolithiasis in children, we detected the biochemical metabolic levels and FokI polymorphisms in the vitamin D receptor (VDR) in Uyghur children with urolithiasis, and evaluated the associations of biochemical metabolic levels with FokI genotypes." (PMID 30742686, 2019). "Finally, there were a number of VDR gene SNPs in the context of urolithiasis risk that could not be included in the meta-analysis due to lack of sufficient amount of data." (PMID 32650740, 2020). "Hence, it could barely implied that VDR gene could not convey a genetic risk factor for urolithiasis, merely regarding our findings." (PMID 32650740, 2020). "A number of genetic markers in different urolithiasis genes including SPP1, VDR, CaSR, urokinase, prothrombin, interleukins and others have been investigated in this regard." (PMID 32842990, 2020). "Therefore, high VDR level might contribute to the development of urolithiasis." (PMID 24093218, 2013).
endothelial dysfunction (16 papers, 2010 to 2025). In vascular diseases, endothelial dysfunction is a systemic pathological state of the endothelium (the inner lining of blood vessels) and can be broadly defined as an imbalance between vasodilating and vasoconstricting substances produced by (or acting on) the endothelium. "Based on the reports of an anti-hypertrophic role of VDR signalling in cardiomyocytes and our own data linking VDR deficiency with endothelial dysfunction, we hypothesised that VDR deficiency would have a detrimental effect on cardiac function post-MI." (PMID 30273386, 2018). "Vitamin D and vitamin D analogs that activate VDR (VDR agonists or activators, VDRAs) have been shown to modulate inflammation, thrombosis, and vasolidation, which are some of the important risk factors associated with endothelial dysfunction." (PMID 20169119, 2010). "The malfunction of 25-hydroxy vitamin D-binding protein binding to the ligand for VDR on the endothelium may contribute to the induction of endothelial dysfunction by a deficiency of 1,25 (OH) 2D3, which cannot effectively act as a ligand for the 25-hydroxy vitamin D receptor (VDR)." (PMID 36500994, 2022). "In early CKD one of the first serum parameters to be altered is a decrease in the serum 1,25-dihydroxyvitamin D3 levels, which raises the question of whether deficient VDR activation may be one of the renal specific risk factors for endothelial dysfunction in CKD." (PMID 20169119, 2010). "Deletion of the VDR gene in endothelial cells lead to endothelial dysfunction (impaired blood vessel relaxation)." (PMID 32164233, 2020). "Vitamin D can then play a variety of biological effects on CVD development via VDR signals, including anti-vascular inflammation and endothelial dysfunction." (PMID 31120983, 2019). "Since endothelial dysfunction is also present in the varicose veins, the finding of VDR venous expression suggests that vitamin D may influence the vein function and/or remodelling in this widespread pathology." (PMID 40261445, 2025). "The activation of VDR in cardiomyocytes and endothelial cells could regulate vascular tension and smooth muscle contractions, thus providing protective effect on endothelial dysfunction." (PMID 35311238, 2022). "It is conceivable that reduced NO production and endothelial dysfunction might additionally impair cardiac function after MI in VDR mutants." (PMID 30273386, 2018). "Induction of endothelial dysfunction may be also relevant to an inadequate degree of 1,25(OH) 2D3, which cannot efficiently act as a ligand for vitamin Dreceptor (VDR), resulting in the disorder of vitamin D-binding protein binding to the ligand for VDR on the endothelium." (PMID 33292313, 2020). "Moreover, vitamin D and VDR can regulate NO synthesis via regulation of eNOS bioactivity in a PI3K/Akt-dependent manner and prevent oxidative stress-induced endothelial dysfunction." (PMID 37760823, 2023).
hyperphosphatemia (16 papers, 2013 to 2025). Abnormally high level of phosphate in the blood. "The management of SHPT is based on avoiding hyperphosphatemia and decreasing PTH levels by administrating calcimimetics and, when needed, VDR activators." (PMID 32913635, 2020). "In those cell types, FGF23 expression is stimulated by the calcitriol (via the vitamin D receptor [VDR] signaling pathway) and hyperphosphatemia (via the sensing of extracellular phosphate levels mediated by type III sodium-dependent phosphate transporter [PiT2]) and FGFR1c." (PMID 35269640, 2022). "Of note, 2 of 4 1α,25(OH)2D3 -treated control mice exhibited severe hyperphosphatemia (>30 mg/dL), whereas 1α,25(OH)2D3 did not induce hyperphosphatemia in any of the Ob-VDR-cKO mice." (PMID 32987399, 2020).
non-small cell lung carcinoma (16 papers, 2010 to 2025). A group of at least three distinct histological types of lung cancer, including non-small cell squamous cell carcinoma, adenocarcinoma, and large cell carcinoma. "We previously reported that non-small cell lung cancer (NSCLC) cells which harbor epidermal growth factor receptor (EGFR) mutations display elevated VDR expression (VDRhigh) and are vitamin D-sensitive." (PMID 24217116, 2013). "In patients with advanced non-small-cell lung cancer, vitamin D receptor (VDR) polymorphisms and haplotypes are reported to be associated with survival." (PMID 22242137, 2011). "In a study of early-stage non-small cell lung cancer patients, higher circulating 25(OH)D, specific vitamin D receptor (VDR) genetic variants, and high vitamin D intakes combined with surgery in the summer were associated with improved survival." (PMID 21695165, 2011). "Recently, single nuclear polymorphisms of the vitamin D receptor were reported to strongly affect survival among patients with non-small-cell lung cancer." (PMID 20594355, 2010). "In non-small cell lung cancer, reduced VDR expression can limit vitamin D’s antiproliferative effects." (PMID 41515234, 2025). "Some SNPs on VDR, GC, CYP2R1, CYP24A1, and CYP27B1 were associated with higher risk of non-small cell lung cancer (NSCLC) in Chinese people, and some SNPs on CYP2R1 and CYP27B1 were associated with the rate of FEV1 change over a ten-year period." (PMID 30249031, 2018). "Some VDR variants, but not circulating 25(OH)D, were associated with improved survival in advanced non-small cell lung cancer patients." (PMID 21695165, 2011). "It is interesting to note that 25-hydroxyvitamin D3 activates vitamin D receptor target gene expression and suppresses EGFR mutant non-small cell lung cancer growth." (PMID 27513329, 2016).
osteomalacia (16 papers, 2011 to 2024). Disorder caused by an interruption of the mineralization of organic bone matrix leading to bone softening, bone pain, and weakness. "The resulting interplay between vitamin D, VDR and the promoter/repressor proteins plays a crucial role in influencing bone mineral density, with its deficiency causing rickets and osteomalacia in children and osteomalacia in adults." (PMID 38474807, 2024). "25D is a low-affinity ligand for the VDR, and it was shown that high amounts of 25D can replace the need for 1,25D for the regulation of calcium homeostasis and osteomalacia." (PMID 35893921, 2022). "Steroid and xenobiotic receptor and vitamin D receptor crosstalk mediates CYP24 expression and drug-induced osteomalacia." (PMID 34955099, 2021).
steatosis (16 papers, 2015 to 2025). Increased lipid within the cytoplasm of cells. "In the liver’s physiological context, hepatocytes normally express low levels of VDR; expression increases in NAFLD but decreases in NASH and chronic hepatitis C. VDR activation in hepatocytes has been linked to lipid accumulation and may contribute to steatosis." (PMID 41041128, 2025). "Hepatic VDR expression is negatively correlated with the severity of steatosis and lobular inflammation in liver histology." (PMID 40547375, 2025). "Human studies have shown inverse correlations between VDR expression and the severity of steatosis and lobular inflammation." (PMID 38509247, 2024). "Increased ANGPTL8 mRNA and protein levels and a positive correlation between ANGPTL8 mRNA and VDR mRNA and the degree of steatosis were found in NAFL patients." (PMID 37175993, 2023). "Remarkably, the vitamin D receptor (VDR) signaling pathway, whose activation in LMs ameliorates liver inflammation and steatosis, was enriched in the rhythmicity-lost genes." (PMID 37066875, 2023). "An association between VDR gene polymorphisms and NAFLD-related liver complications, including steatosis, cirrhosis, and HCC, was reported." (PMID 37175993, 2023). "Activation of VDR in hepatic macrophages via its cognate ligand has been uncovered to ameliorate steatosis and insulin resistance in experimental studies." (PMID 34067649, 2021). "Previous work from this group found that vitamin D receptor is highly expressed in the distal region of the small intestine and vitamin D signaling can protect the host from steatosis." (PMID 34764881, 2021). "VDR expression on cholangiocytes was inversely correlated with steatosis severity, lobular inflammation and NAFLD score, and expression of CYP2R1 in hepatocytes of NASH patients correlated strongly with VDR positivity on liver inflammatory cells." (PMID 25951129, 2015). "Patients with NAFLD have 26% additional risk to VDD as compared to controls owing to the impairment of 25 (OH)D synthesis due to the presence of steatosis, in addition vitamin D receptor (VDR) expression in the hepatocytes decreases as the extent of the disease increase." (PMID 36998617, 2023). "Steatosis may be influenced by VDR SNPs, as the presence of GA/AA genotypes of the FokI SNP was associated with increased severity of steatosis in pediatric patients with NAFLD in the United Kingdom." (PMID 37175993, 2023). "The elevated serum VD level might alleviate inflammation/steatosis of the liver and improve insulin sensitivity by activating liver macrophage vitamin D receptors (VDR)." (PMID 36172527, 2022). "We, therefore, hypothesized that one potential mechanism of VPA-induced steatosis could be through induction of the pro-lipogenic VDR gene." (PMID 35807853, 2022). "Concluding, they suggest that therapeutic inhibition of liver VDR may have beneficial effects regarding steatosis in early NAFLD." (PMID 34827697, 2021). "In humans, hepatic VDR expression is inversely correlated with steatosis severity." (PMID 34067649, 2021). "ANGPTL3 correlated with the degree of steatosis and the expression of LPL, VDR, and enzymes related to vitamin D and cholesterol metabolism (CYP27A1 and CYP2R1)." (PMID 37175993, 2023).